UBE2F (ubiquitin conjugating enzyme E2 F (putative))
Description:
Accepts the ubiquitin-like protein NEDD8 from the UBA3-NAE1 E1 complex and catalyzes its covalent attachment to other proteins. Together with the E3 ubiquitin ligase RNF7/RBX2, specifically neddylates cullin-5 (CUL5). Does not neddylate CUL1, CUL2, CUL3, CUL4A or CUL4B. Mediates neddylation of the CUL9-RBX1 complex. (Microbial infection) Following infection by HIV-1 virus, participates to HIV-1 Vif protein-mediated ubiquitination and degradation of APOBEC3G by mediating neddylation of cullin-5 (CUL5).
Synonyms: NCE2
Tractability: PROTAC: ubiquitination databases record sites on it; its protein half-life has been measured.
Target class: Enzyme; Transferase
Gene: Protein-coding gene on chromosome 2 (237,966,827 to 238,045,486, forward strand). Ensembl gene ENSG00000184182.
Subcellular location (Human Protein Atlas): Cytosol
Pathways (Reactome):
Immune System: Antigen processing: Ubiquitination & Proteasome degradation
Metabolism of proteins: Neddylation
Gene Ontology:
Molecular function: NEDD8 conjugating enzyme activity; protein binding; NEDD8 transferase activity
Biological process: protein neddylation; post-translational protein modification
Cellular component: cytosol
Genetic constraint (gnomAD): Loss-of-function variants: 0 observed, 20.11 expected, observed/expected ratio (o/e) 0, 90% interval 0 to 0.15. The upper end of that interval is the gene's LOEUF score, 0.15, which puts it in group 1 of 6, group 1 being the genes least tolerant of losing a copy. Missense variants: 109 observed, 193.27 expected, observed/expected ratio (o/e) 0.56, 90% interval 0.48 to 0.66. Synonymous variants: 54 observed, 69.96 expected, observed/expected ratio (o/e) 0.77, 90% interval 0.62 to 0.97.
Homologues: Orthologues: chimpanzee UBE2F (100% identical), guinea pig UBE2F (99% identical), dog UBE2F (97% identical), mouse Ube2f (97% identical), rat Ube2f (96% identical), tropical clawed frog ube2f (90% identical), zebrafish ube2f (82% identical), macaque UBE2F (75% identical), Caenorhabditis elegans ubc-12 (47% identical). Paralogues in human: CDC34 (29% identical), UBE2R2 (28% identical), UBE2G1 (27% identical), UBE2J1 (25% identical), UBE2K (25% identical), UBE2I (24% identical), UBE2N (24% identical), UBE2O (23% identical), UBE2Z (23% identical), UBE2S (22% identical), UBE2U (22% identical), UBE2B (22% identical), and 12 more.
Diseases named in the same sentence as UBE2F in open-access papers:
UBE2F is named in the same sentence as 31 diseases in open-access papers, as found by Europe PMC text mining. Sharing a sentence is not in itself a finding about the gene and the disease. The quoted sentences say what the papers report.
lung carcinoma (16 papers, 2019 to 2026). "We then measured possible apoptosis induction, using cleaved caspase-3 and PARP as the readouts, given our previous study showing that UBE2F knockdown induced robust apoptosis in lung cancer cells via causing NOXA accumulation." (PMID 39762645, 2025). "Jia's group found that the upregulation of UBE2F was a critical approach for lung cancer cells to escape platinum-induced cell apoptosis, causing insensitivity to platinum-based chemotherapy." (PMID 37771770, 2023). "UBE2F upregulation allows lung cancer cells to evade apoptosis caused by platinum exposure." (PMID 36690633, 2023). "A previous study showed that UBE2F promotes the survival of lung cancer cells by activating CRL5 to degrade NOXA via the K11 Linkag." (PMID 40699886, 2025). "In lung cancer tissues, high levels of UBE2F and CUL5 correlate with reduced NOXA levels and poorer survival in patients." (PMID 40699886, 2025). "Consistently, we found that a small molecule neddylation inhibitor of UBE2F-Cullin-5 effectively sensitized lung cancer cells to radiation." (PMID 39762645, 2025). "Our previous studies showed that UBE2F knockdown suppressed growth and survival of lung cancer cells via inducing NOXA accumulation to induce apoptosis." (PMID 39762645, 2025). "The upregulation of the NEDD8-binding enzyme UBE2F is a significant pathway for lung cancer cells to evade platinum-induced apoptosis." (PMID 38235113, 2023). "In lung cancer cells, overexpression of UBE2F activates CRL5 and promotes NOXA degradation, leading to inhibition of apoptosis and improvement of cell survival." (PMID 36690633, 2023). "UBE2F overexpression contributed to lung cancer cell proliferation in vitro and in vivo, while its downregulation effectively inhibited tumor growth." (PMID 37771770, 2023). "In lung cancer cells, depletion of UBE2F renders the cells more sensitive to multiple anti-tumor agents (e.g., an inhibitor of anti-apoptotic protein MCL1) by accumulating NOXA." (PMID 36690633, 2023). "In vitro and in vivo studies have demonstrated that UBE2F overexpression promotes lung cancer formation, whereas UBE2F knockdown impedes tumor growth." (PMID 37717015, 2023). "Next, we determined the effect of HA-9104 on the cellular levels of UBE2F in several lines of lung cancer cells." (PMID 36253371, 2022). "Our previous study validated that the neddylation E2 UBE2F is a promising therapeutic target in lung cancer." (PMID 36253371, 2022). "UBE2F promotes lung cancer cell survival by mediating the ubiquitination and degradation of the pro-apoptotic protein, NOXA, in a UBE2F/SAG/CUL5-dependent manner." (PMID 34199813, 2021). "The overexpression of UBE2F enhances lung cancer growth both in vitro and in vivo, whereas silencing of UBE2F suppresses tumor growth." (PMID 34199813, 2021). "This study is directed toward understanding how UBE2F responds to platinum-based chemotherapy and then allows for the platinum-insensitivity of lung cancer cells." (PMID 33184273, 2020). "UBE2F knockout (KO) mildly affected the proliferation of lung cancer cells, but sharply promoted the inhibition of proliferation induced by cisplatin or carboplatin at a low dose, compared with wild-type (WT) since day 5 of giving drugs." (PMID 33184273, 2020). "Here, we report that the upregulation of the NEDD8-conjugating enzyme UBE2F is an important way for lung cancer cells to escape platinum-induced cell apoptosis, which confers to insensitivity to platinum-based chemotherapy." (PMID 33184273, 2020). "Furthermore, a genome-wide CRISPR inhibition (CRISPRi) screen conducted in lung cancer cells demonstrated that knockout of CUL5, RBX2, or UBE2F (a specific E2 for CRL5 E3s) caused cells to become hypersensitive to a CDK9 inhibitor or MCL-1 inhibitor." (PMID 40699886, 2025). "Deletion of UBE2F could sensitize lung cancer cells to platinum treatment by increasing the protein levels of pro-apoptotic protein NOXA and subsequently inducing cell apoptosis." (PMID 37771770, 2023).
lung carcinoma (continued). "Moreover, UBE2F was upregulated by platinum chemotherapy and its knockdown sensitized lung cancer cells to platinum treatment by elevating NOXA protein levels and stimulating cell apoptosis." (PMID 34199813, 2021). "To this end, we generated stable A549 cells with UBE2F knockout by CRISPR/Cas9 system to determine whether UBE2F deletion allows for the platinum sensitivity for lung cancer cells." (PMID 33184273, 2020). "Therefore, as the apoptotic regulatory protein, the role of UBE2F in the chemosensitivity of lung cancer cells to platinum is worth further investigation." (PMID 33184273, 2020). "Our observations uncover a previously unknown regulatory mechanism of UBE2F stability upon platinum chemotherapy and suggest that UBE2F might be a novel therapy target for sensitizing lung cancer cells to platinum-based chemotherapy." (PMID 33184273, 2020). "Given that transcriptional activation of NOXA is critical for cisplatin-induced apoptosis, the accumulation of UBE2F might have a potential role in the resistance of platinum drugs via inhibiting NOXA in lung cancer chemotherapy." (PMID 33184273, 2020). "Additionally, knockout of UBE2F significantly sensitizes lung cancer cells to platinum treatment by enhancing the protein levels of NOXA and subsequently promoting cell apoptosis." (PMID 33184273, 2020). "Based on our data, patients with lung cancers that exhibit loss of function mutations in either CUL5, RNF7, UBE2F or Elongin B that coincide with high expression of MCL1/Bcl-xL could be good candidates for treatment with CDK9i or MCL1i." (PMID 31294695, 2019). "For example, the small-molecule inhibitor HA-9104 targeting UBE2F selectively inactivates CRL5 and can inhibit lung cancer progression by inducing the accumulation of the pro-apoptotic protein NOXA." (PMID 39062453, 2024). "Importantly, besides lung cancer cells, multiple cancer cells, including ovarian cancer cells and breast cancer cells, all could upregulate the expression of UBE2F responding to platinum treatments, suggesting UBE2F may be a potentially universal drug target of platinum-sensitization." (PMID 33184273, 2020). "UBE2F facilitates CUL5 neddylation and activation, which ubiquitinates and degrades pro-caspase 3, IκBα, and NOXA, thus inducing adaptive radioresistance in lung cancer." (PMID 41540013, 2026). "Additionally, UBE2F-mediated neddylation activates CRL5, enhancing the ubiquitination and degradation of NOXA, thereby facilitating apoptosis resistance in lung cancer and CRC." (PMID 41540013, 2026). "Similarly, CUL5 neddylation enhances CRL5 activity through the UBE2F/SAG/CUL5 complex, thus ubiquitylating NOXA at K11 in the proteasomal degradation pathway in lung cancer." (PMID 41540013, 2026). "Further characterization of nature of growth inhibition revealed that unlike lung cancer cells, UBE2F knockdown in liver cancer cells did not induce apoptosis, rather reduced the cell size and induced autophagy, the signs of mTORC1 inactivation." (PMID 39762645, 2025). "Upon hypoxia or mitogen stimulation, UBC12 acted as a dual E2 complexed with DJ-1/Parkin to enhance ubiquitylation and degradation of UBE2F, further resulting in CRL5 inactivation, the pro-apoptotic protein NOXA accumulation and the growth inhibition of lung cancer cells." (PMID 37771770, 2023).
lung adenocarcinoma (3 papers, 2020 to 2022). A carcinoma that arises from the lung and is characterized by the presence of malignant glandular epithelial cells. "To examine the correlation of UBE2F and RBX1 expressions in clinical samples of human lung adenocarcinoma, we collected a total of 20 lung adenocarcinoma tissues and performed a direct immunoblotting analysis to determine the protein levels of UBE2F and RBX1." (PMID 33184273, 2020). "We observed a reduction in RBX1 expression is in parallel with an increase in UBE2F expression in lung adenocarcinoma tissues." (PMID 33184273, 2020). "Using the Pearson correlation methods, we found that the protein levels of UBE2F vs. RBX1 exerted a significantly negative correlation in 20 lung adenocarcinoma samples (Pearson R = −0.52, P = 0.019)." (PMID 33184273, 2020).
non-small cell lung carcinoma (3 papers, 2020 to 2026). A group of at least three distinct histological types of lung cancer, including non-small cell squamous cell carcinoma, adenocarcinoma, and large cell carcinoma. "Specifically, UBE2F upregulation enhances the neddylation levels and CUL5 activity, thereby reinforcing CRL5-mediated degradation of NOXA and leading to platinum and etoposide resistance in non-small cell lung cancer (NSCLC) and CRC." (PMID 41540013, 2026). "Both cisplatin and carboplatin treatments in A549 and H1299, two human non-small cell lung cancer cell lines, led to the obvious accumulation of UBE2F in a dose-dependent manner, but not other neddylation components (e.g., E1: NAE1 and UBA3; E2: UBE2M; E3: RBX1 and RBX2)." (PMID 33184273, 2020).
psoriasis (3 papers, 2024 to 2025). An autoimmune condition characterized by red, well-delineated plaques with silvery scales that are usually on the extensor surfaces and scalp. "The random forest algorithm further identified 28 genes significantly associated with psoriasis, including FABP5, CD47, and UBE2F." (PMID 38596682, 2024). "We identified 34 housekeeping genes associated with psoriasis and observed that the co-expression relationships between six genes (APOL2, DCUN1D3, UBE2F, HIGD1A, PPIF, and STAT3) and known psoriasis-related genes differed significantly between diseased and healthy individuals." (PMID 40959079, 2025). "Similarly, CD47 and UBE2F are involved in aberrant functions of DCs and T cells in various tumors, indicating their potential relevance to psoriasis development." (PMID 38596682, 2024).
breast carcinoma (2 papers, 2020 to 2022). "We also found that neither the SPOP-ASCT2 axis, nor NEDD8 and few neddylation enzymes, including E1 heterodimer NAE1/APPBP1, and UBA3/NAEβ, and two E2s, UBE2M and UBE2F is subjected to regulation by glucose deprivation in breast cancer cells." (PMID 35641493, 2022).
liver cancer (2 papers, 2022 to 2025). An epithelial or non-epithelial malignant neoplasm that arises from the liver. "We next investigated the role of UBE2F in growth regulation of liver cancer cells using the in vitro cell culture models with a loss-of-function approach." (PMID 39762645, 2025). "Biologically, UBE2F knockdown in liver cancer cells inactivates mTORC1 to suppress cell growth, reduce cell size and induce autophagy, whereas liver-specific Ube2f deletion significantly inhibits liver steatosis and tumorigenesis induced by Pten loss." (PMID 39762645, 2025). "Among three liver cancer cell lines tested, UBE2F knockdown induced modest apoptosis in PLC/PRF/5 cells, but not at all in SK-HEP-1 and Hep3B cells (Fig. EV1G)." (PMID 39762645, 2025). "To determine the biological significance, we used few lines of liver cancer cells and showed that UBE2F knockdown suppresses the growth and survival of liver cancer cells, indicating its growth-essential role." (PMID 39762645, 2025). "To this end, we first analyzed the TCGA liver cancer database, and found that compared to normal liver tissue, UBE2F is overexpressed in liver cancer tissues, which is positively correlated with the poor survival of patients." (PMID 39762645, 2025). "We further observed that Ube2f deletion triggered remarkable hepatic cystogenesis in this Pten-null liver cancer model." (PMID 39762645, 2025). "Moreover, treatment of liver cancer cells with 3-MA, an inhibitor of autophagy induction, caused significant alleviation of LC3-II accumulation triggered by UBE2F knockdown, indicating a causal involvement of autophagy induction." (PMID 39762645, 2025). "Whether and how UBE2F is altered in liver cancer to regulate cell growth and survival and to affect liver tumorigenesis are previously unknown." (PMID 39762645, 2025). "Finally, a positive correlation between UBE2F levels and mTORC1 activity (pS6) was observed in human liver cancer tissues." (PMID 39762645, 2025). "More interestingly, UBE2F knockdown-induced mTORC1 inactivation was in a manner independent of growth factors, since the same phenomenon was observed in all three lines of liver cancer cells after 24 h of serum starvation (Fig. EV2H), indicating that UBE2F regulates the intrinsic activity of mTORC1." (PMID 39762645, 2025). "Whether and how UBE2F regulates growth of liver cancer cells and liver tumorigenesis is previously unknown." (PMID 39762645, 2025). "The findings presented in this study further suggested that MLN4924 could potentially enhance the efficacy of anticancer therapies in liver cancers with high UBE2F levels, an interesting subject for future study." (PMID 39762645, 2025). "We then used liver tumor tissue microarray, and found that the UBE2F staining were also significantly higher in tumor tissues, as compared with adjacent normal tissues, and again higher UBE2F protein levels correlated with a worse survival of liver cancer patients." (PMID 39762645, 2025). "Thus, the major cause of growth inhibition upon UBE2F knockdown was not due to apoptosis in liver cancer cells." (PMID 39762645, 2025). "Thus, our study revealed a novel mechanism by which neddylation activates the RHEB-mTORC1 signaling pathway, and provided proof-of-concept evidence that the UBE2F-SAG axis could be an attractive anti-liver cancer target." (PMID 39762645, 2025). "Finally, we determined whether UBE2F regulation of the mTORC1 signal can be extended to human liver cancer tissues." (PMID 39762645, 2025). "Thus, targeting the UBE2F-SAG axis may have therapeutic implications for the treatment of non-alcoholic fatty liver disease and liver cancer with activated mTORC1 signal as a result of PTEN loss." (PMID 39762645, 2025). "Finally, a positive correlation between high UBE2F levels and more active mTORC1 in human liver tumor tissues highly suggests that UBE2F overexpression seen in liver cancer tissue is not merely a consequence, rather causally related to liver tumorigenesis in humans." (PMID 39762645, 2025).
liver cancer (continued). "The follow-up biochemical studies confirmed mTORC1 inactivation, as evidenced by reduced levels of p4E-BP1 and pS6K in both liver cancer cells and MEF cells upon UBE2F knockdown or knockout, respectively." (PMID 39762645, 2025). "Importantly, under unstressed physiological condition, endogenous SAG bound to endogenous RHEB, but neither SAG nor RHEB binds to UBE2F or mTOR in these liver cancer cell lines." (PMID 39762645, 2025).
autoimmune disease (1 paper, 2023). A disorder resulting from loss of function or tissue destruction of an organ or multiple organs, arising from humoral or cellular immune responses of the individual to their own tissue constituents. "To verify the functional relationship between neddylation and CRLs in Treg cells, we compare the degree of autoimmune disorders and transcriptional alterations caused by Ube2m&Ube2f versus Rbx1&Sag deficiency in Treg cells." (PMID 37600496, 2023). "Double deletion of neddylation E2s Ube2m&Ube2f or E3s Rbx1&Sag in Treg cells leads to the impairment of suppressive function of Treg cells and results in severe autoimmune disorders, fully demonstrating the pivotal role of the neddylation-CRL axis in the maintenance of Treg cell fitness." (PMID 37600496, 2023).
colitis (1 paper, 2023). Inflammation of the colon. "We found that such colitis was prevented by simultaneous transfer of Treg cells from wild-type mice, but not from Ube2m&Ube2f-deficient mice, demonstrating that double deletion of neddylation E2s impairs the suppressive function of Treg cells." (PMID 37600496, 2023).
hepatocellular carcinoma (1 paper, 2025). A malignant tumor that arises from hepatocytes. "Finally, UBE2F expression levels and mTORC1 activity correlate with patient survival in hepatocellular carcinoma." (PMID 39762645, 2025). "Collectively, our study identifies RHEB as neddylation substrate of the UBE2F-SAG axis, and highlights the UBE2F-SAG axis as a potential target for the treatment of non-alcoholic fatty liver disease and hepatocellular carcinoma." (PMID 39762645, 2025).
pancreatic cancer (1 paper, 2025). "Our most recent study showed that UBE2F knockdown inhibited growth and survival of pancreatic cancer cells in vitro, and suppressed pancreatic tumorigenesis induced by KrasG12D in vivo via inducing accumulation of DIRAS2, a RAS inhibitor to block the MAPK/c-Myc signals." (PMID 39762645, 2025).
Sepsis (1 paper, 2026). Sepsis is defined as life-threatening organ dysfunction caused by a dysregulated host response to infection. "Notably, UBE2F showed the strongest upregulation and functional relevance in sepsis models." (PMID 42099630, 2026).
steatosis (1 paper, 2025). Increased lipid within the cytoplasm of cells. "Furthermore, liver-specific Ube2f knockout attenuates steatosis and tumorigenesis induced by Pten loss in an mTORC1-dependent manner, suggesting a causal role of UBE2F in liver tumorigenesis." (PMID 39762645, 2025).